CTLA4 (cytotoxic T-lymphocyte associated protein 4)
Diseases named in the same sentence as CTLA4 in open-access papers (continued):
Sharing a sentence is not in itself a finding about the gene and the disease.
breast carcinoma (continued). "Furthermore, we further analysis the correlation of risk score and immune checkpoint in breast cancer and demonstrated that most of key checkpoint were significantly differentially expressed between the two groups in breast cancer patients, including CD44, TIGIT, CTLA4, CD274, CD86 and CD80." (PMID 35052427, 2021). "So far, many breakthroughs have been made in immunotherapy of breast cancer, for instance, the use of monoclonal antibodies specifically recognizing antigens on tumor cells (e.g., HER2) or the development of specific antibodies targeting immune checkpoints (e.g., PD-L1, PD-1, CTLA4)." (PMID 34885122, 2021). "Finally, we performed immunohistochemistry with breast cancer tissue samples and observed that CXCL9 is highly expressed in the ER-negative subgroup and positively correlated with the immune-related factors LAG3, PD1, PDL1 and CTLA4 to varying degrees." (PMID 34527583, 2021). "CDF1 mice, with 200 mm3 C3H mammary carcinomas in the right rear foot, were intraperitoneally injected with combretastatin A-4 phosphate (CA4P), its A-1 analogue OXi4503, and/or checkpoint inhibitors (anti-PD-1, PD-L1, or CTLA-4 antibodies), administered twice weekly for two weeks." (PMID 32640548, 2020). "Therefore, from the conclusion that CTLA-4 is highly expressed in TNBC, we speculate that compared with other types of breast cancer, CTLA-4 has potential value in exploring immunotherapy for TNBC." (PMID 33033520, 2020). "Thus, CTLA-4 blockade is a promising approach for therapeutic studies in breast cancer patients, with or without combination with immunotherapy." (PMID 31430935, 2019). "In this study, anti-CTLA-4 immunotherapy was combined with tremelimumab and exemestane and an elevation in the levels of peripheral CD4+ and CD8+ T cells, which express inducible co-stimulatory molecules (ICOS), was observed, suggesting a role for anti-CTLA-4 inhibitors in breast cancer treatment." (PMID 31366131, 2019). "In addition, this study also demonstrates that the CTLA-4 haplotypes, ATCGA and ATCAG, may have a protective role in breast cancer." (PMID 17825114, 2007). "Moreover, RAPA-201 therapy, which has been thought to block the expression of PD-1, CTLA-4, TIM-3, and LAG3, thereby improving the immune suppressive tumor microenvironment, is currently being trialed in a phase I/II study for patients with solid cancer (including breast cancer) (NCT05144698)." (PMID 36765782, 2023). "Furthermore, our results suggest that the CTLA4-inhibitor ipilimumab, or inhibitors of B7-H3 or TIM-3 that are currently in clinical development, may be more effective in combination with ET compared with PD-1 or PD-L1 inhibitors in HR+ breast cancer." (PMID 37450351, 2023). "Ideally, a basket trial specifically for patients with low- and/or intermediate-positive breast cancer could provide answers on this question, testing neo-adjuvant ICB-combinations such as anti-PD1 plus endocrine treatment or ICB with other immuno-oncology agents such as anti-CTLA4 plus anti-PD154." (PMID 37179445, 2023). "However, no CTLA-4 inhibitor has been approved for the treatment of breast cancer." (PMID 33033520, 2020). "It is possible that isolated CTLA-4 positive breast cancer cells could have a different responsiveness to ipilimumab or hyperglycemia; further studies will be performed on isolated CTLA-4 + breast cancer cells, studying their metabolism and their responsiveness to glucose and growth factors." (PMID 33096896, 2020). "Furthermore, PD-1+ T cells do not co-express LAG-3, TIM-3 or CTLA-4, which may suggest that PD-1+ T cells in breast cancer may not suffer from exhaustion, or at least support the argument that PD-1 expression alone does not indicate T cell exhaustion." (PMID 30728081, 2019). "The investigators analyzed a large dataset of 2,881 ICI-treated (PD-1/PD-L1 inhibitor or CTLA-4 inhibitor or a combination of both) and 841 non-ICI-treated patients across 18 solid tumor types, including breast cancer." (PMID 40405250, 2025).
breast carcinoma (continued). "The results showed that in breast cancer, GPS1 expression was positively correlated with LAG3, PVRL2, and LGALS9, and negatively correlated with CD274 and HAVCR2, but not with CTLA4 and PDCD1." (PMID 38289496, 2024). "Of note, our study was not designed to tease apart the individual contributions of anti-PD-1 and anti-CTLA-4 on Tregs, since anti-CTLA-4 is rarely used for the treatment of breast cancer patients without the addition of anti-PD-1." (PMID 37089449, 2023). "Due to the observed role of TILs in breast cancer progression, albeit not completely well-defined, and an understanding of the immunoediting hypothesis, several immune checkpoint inhibitors against PD-1, PD-L1 and CTLA-4 have been tested in the treatment of the disease." (PMID 37662839, 2023). "Several of the immune genes were expressed at a significantly lower level in the resistant than sensitive mammary tumors in the HFD offspring not treated with genistein: Foxp3 (p = 0.012), Tgfb1 (p < 0.001), Ctla4 (p = 0.023) and Il6 (p = 0.018)." (PMID 33440675, 2021). "Next, we examined the expression of PD-1, CTLA-4, LAG-3, TIM-3, FoxP3, and Helios in CD4+CD25− T cell subset in the presence or absence of breast cancer cells." (PMID 31614877, 2019). "Breast cancer cells also upregulated the expression of PD-1, TIM-3 and/or LAG-3, but not CTLA-4, in CD4+CD25+ T cells (comprising of activated T cells and Tregs)." (PMID 31614877, 2019). "In breast cancer, NAC has been well documented to significantly reduce tumour- infiltrating FOXP3+, CTLA-4+ and PD-1+ T cells (but not CD8+ T cells)." (PMID 29390966, 2018). "There is a plethora of research on multiple combination therapies with anti-CTLA-4 antibodies + anti-PD-1/PD-L1 antibodies + other agents, and researchers have combined anti-CTLA-4 antibodies with multiple other agents for breast cancer treatment without the use of anti-PD-1/PD-L1 antibodies." (PMID 37860188, 2023). "The soluble CTLA-4 levels were low, which might reflect the clinical situation, as anti-CTLA-4 immunotherapy is not yet suitable for the treatment of breast cancer patients." (PMID 37174080, 2023). "Previous studies have shown that approximately 50% of PD-L1 transmembrane proteins in breast cancer with androgen receptor (AR)-negative prevalence and TNBC cells express PD-L1, whose receptor is PD-1, and also bind PD-L2 as other ligands, and express CTLA-4." (PMID 34198652, 2021). "Interestingly, a-CTLA4-TGFβRII was able to exhibit superior single agent activity against PD-L1-expressing tumors and the addition of a-PD1 antibody did not significantly enhance its antitumor efficacy in the breast cancer model." (PMID 29467463, 2018). "However, in peripheral blood mononuclear cells of patients with breast cancer, PD-L1 and TIGIT expressions could be regulated by DNA methylation epigenetic machinery; however, no changes in Tim-3, CTLA-4, and LAG-3 expressions were observed compared to those in healthy donors." (PMID 34504800, 2021).
autoimmune disease (425 papers, 2005 to 2026). A disorder resulting from loss of function or tissue destruction of an organ or multiple organs, arising from humoral or cellular immune responses of the individual to their own tissue constituents. "Specifically, the CT60 A/G polymorphism impacts the expression levels of soluble CTLA-4, potentially enhancing susceptibility to autoimmune diseases by altering the ratio of transmembrane to soluble forms of the protein." (PMID 40282351, 2025). "CTLA-4 is associated with various autoimmune diseases; however, the relationship between CTLA-4 polymorphisms and AAV in the Guangxi population of China remains underexplored." (PMID 41000380, 2025). "The translational implications of genetic variants in the CTLA-4 locus, particularly concerning their association with autoimmune diseases, are significant for personalized medicine and therapeutic interventions." (PMID 40282351, 2025). "It was first implicated in CTLA-4 trafficking following reports of LRBA-deficient patients who developed autoimmune disorders resembling CTLA-4 deficiency." (PMID 41031910, 2025). "Several CTLA4 genetic variants have been associated with autoimmune disease including two single-nucleotide (SNP) variants located in the non-coding region (rs3087243, rs5742909) and one SNP in the coding region, rs231775." (PMID 40862794, 2025). "Known risk factors include a history of comorbid autoimmune disease, use of CTLA-4 inhibitors, and chronic kidney disease stage 3 or higher." (PMID 41394799, 2025). "Research into CTLA-4’s immunosuppressive role has demonstrated that CTLA-4 deficient mice develop unregulated T-cell proliferation and autoimmune disorders." (PMID 40507328, 2025). "The essential role of CTLA-4 has been associated with several autoimmune diseases, such as Hashimoto’s disease and Graves’ disease, autoimmune hemolytic anemia, hypogammaglobulinemia, and B cell lymphopenia." (PMID 40574024, 2025). "Although CTLA-4 gene polymorphisms and sCTLA-4 have been investigated in autoimmune diseases and a few malignancies, their contribution to HCC development in the context of HCV infection remains poorly defined." (PMID 41303553, 2025). "Genome-wide association studies (GWAS) have already identified shared susceptibility loci across multiple autoimmune diseases, including variants in HLA regions, CTLA4, and IL2RA, suggesting common immunoregulatory pathways." (PMID 40787461, 2025). "The germline CTLA4 rs231775 polymorphism has been implicated in autoimmune diseases and cancer risk." (PMID 40862794, 2025). "The regulatory T cells (Treg cells) inhibit autophagy in DCs in a cytotoxic T lymphocyte-associated protein 4-dependent (CTLA4-dependent) manner, thereby effectively suppressing inflammatory response-mediated autoimmune disorders." (PMID 40842999, 2025). "CTLA-4 inhibitors, combination regimen, previous irAE, and a history of autoimmune disease represent the most recognized risk factors." (PMID 39796705, 2024). "Single nucleotide polymorphisms in exon 1 of CTLA-4 have been linked to susceptibility to several autoimmune diseases, including multiple sclerosis." (PMID 38807592, 2024). "CTLA4 is constitutively expressed on regulatory T cells (Tregs), is crucial to their suppressive capabilities, and is a recurrently associated locus with autoimmune diseases, including AAD." (PMID 38562931, 2024). "Animal studies showed that while CTLA-4 deficiency is associated with lethal, early-onset lymphoproliferative conditions, PD-1 deficiency generates more indolent autoimmune diseases." (PMID 38541099, 2024). "The cytotoxic T lymphocyte-associated antigen-4 (CTLA4) gene, a member of the immunoglobulin superfamily, is crucial for maintaining immune homeostasis and preventing autoimmune diseases." (PMID 39456732, 2024).
autoimmune disease (continued). "Single‐nucleotide polymorphisms (SNPs) of the CTLA-4-encoding genes are involved in the pathogenesis of many autoimmune diseases such as systemic lupus erythematosus (SLE) and rheumatoid arthritis (RA)." (PMID 38485815, 2024). "Studies have indicated that overexpression or functional defects in CTLA4 can disrupt immune tolerance and increase the risk of autoimmune diseases, including systemic lupus erythematosus." (PMID 39456732, 2024). "Cytotoxic T lymphocyte‐associated antigen‐4 (CTLA‐4) plays a central role in immune checkpoint pathways and preventing autoimmune diseases by regulating immune tolerance." (PMID 38485815, 2024). "Heterozygous mutations in CTLA-4 have been associated with a spectrum of clinical manifestations, including autoimmune disorders targeting specific organs, hypogammaglobulinemia, recurrent infections, and susceptibility to certain cancers." (PMID 39000519, 2024). "Cytotoxic T-lymphocyte-associated protein 4-immunoglobulin (CTLA4-Ig) blocking agents are well tolerated and have been used extensively in patients with autoimmune disease and as post-transplant immunosuppression." (PMID 39076086, 2024). "Researchers have identified genetic variations in the CTLA-4 gene that are associated with an increased activity of T-cells, and can lead to the development of autoimmune disorders such as GD and autoimmune hypothyroidism." (PMID 39359534, 2024). "It is well known that genetic polymorphisms of CTLA-4 and PD-1 genes can increase the risk of developing autoimmune diseases, including IIHs." (PMID 37623461, 2023). "The heterozygous mutations of CTLA-4 in T cells have been reported to be linked to a variety of autoimmune diseases." (PMID 37497212, 2023). "Further supporting this evidence is another meta-analysis that reported that the polymorphism of CTLA-4 + 49 G/A (rs231775) is associated with autoimmune diseases such as T1D, rheumatoid arthritis, and SLE in Asian and Caucasian populations." (PMID 37497212, 2023). "Kartolo and colleagues identified a history of autoimmune disease, use of CTLA‐4‐inhibitors and poor kidney function as risk factors for the development of irAEs." (PMID 37084178, 2023). "The single nucleotide polymorphisms in the CTLA4 gene are associated with several autoimmune disorders such as rheumatoid arthritis, type I diabetes, and systemic lupus erythematosus (SLE)." (PMID 37895245, 2023). "Germline CTLA-4 deficiency causes severe autoimmune diseases characterized by dysregulation of Foxp3+ Tregs, hyper-activation of effector memory T cells, and variable forms autoimmune cytopenia including gradual loss of B cells." (PMID 36909522, 2023). "The functional integrity of the CD28 molecule was necessary for CTLA-4 knockout mice to cause autoimmune diseases, implying that CTLA-4 suppresses the autoimmunity caused by the CD28 signaling pathway." (PMID 37497212, 2023). "Taken together, dysfunctions of CTLA-4 in T cells can cause a breakdown of immunological self-tolerance and result in susceptibility to autoimmune diseases." (PMID 37497212, 2023). "Abatacept, a soluble fusion protein consisting of the extracellular domain of human cytotoxic T-lymphocyte-associated protein 4 (CTLA4), is a selective T-cell costimulation modulator and a protein drug for autoimmune diseases." (PMID 37175882, 2023). "Co-inhibition of PD-1 and CTLA-4 enhances not only antitumor activity but also autoimmune diseases, as observed in mice with PD-1 or CTLA-4 deficiencies." (PMID 37179337, 2023). "There are several CTLA-4 single nucleotide polymorphisms (SNPs) that play crucial roles in numerous autoimmune disorders and cancers." (PMID 38046481, 2023). "Some CTLA-4 polymorphisms are commonly associated with autoimmune disorders, including endocrinopathies (i.e., T1DM, Graves’ disease, autoimmune hypothyroidism, and Addison’s disease)." (PMID 35205804, 2022).
autoimmune disease (continued). "CTLA4 gene, mapped on the 2q33 chromosome, is associated with susceptibility to autoimmunity, with the CTLA4 region as an important locus for autoimmune diseases." (PMID 36142815, 2022). "A large number of studies have revealed the correlation between IRs and autoimmune diseases; CTLA4 and PD1 were associated with AS." (PMID 35769669, 2022). "Although this was relatively modest, even partial CTLA-4 deficiency results in severe autoimmune disease such as in CTLA-4 haploinsufficiency with autoimmune infiltration (CHAI)." (PMID 35197125, 2022). "The key factor behind this induced autoimmune disease is the depletion of the mucosal Treg cells, which is more prevalent in patients with CTLA-4 polymorphism (Y60C)." (PMID 36213163, 2022). "It was revealed that in PD‐1‐deficient mice, autoimmune diseases were commonly concentrated in the organs, while in CTLA-4 deficient mice, autoimmune diseases were wide, systemic, and fetal." (PMID 36420664, 2022). "In 1995, CTLA-4 was reported to be associated with T cells, and in 2000, PD-1 was reported to be involved in autoimmune diseases." (PMID 34811710, 2022). "TLA-4-deficient mice suffer an autoimmune disease characterized by polyclonal T-cell proliferation, which supports a critical role for CTLA-4 in controlling T-cell responses." (PMID 35955790, 2022). "The critical role of CTLA-4 in regulating T cell activation is underscored by the enhanced susceptibility to autoimmune diseases observed in patients harboring mutations in CTLA-4." (PMID 35237846, 2022). "Analysis of mutations especially in the ligand binding domain of CTLA4 protein can disrupt its interaction with ligands which can lead to various autoimmune diseases and also cancer." (PMID 36443461, 2022). "The genetic polymorphisms of the CTLA-4 and of PD-1 genes can increase the incidence of autoimmune disease, including IIH." (PMID 34683167, 2021). "It has been reported that mutations in the CTLA-4 gene are associated with an increased risk of human autoimmune disorders." (PMID 34744733, 2021). "It has been reported that a Treg-specific deficiency of cytotoxic T lymphocyte antigen 4 (CTLA-4) results in development of systemic lymphoproliferation, fatal autoimmune disease, hyperproduction of immunoglobulin E, and potent tumor immunity." (PMID 34084175, 2021). "CTLA-4 is mainly expressed on T-regulation cells and functions as an immune checkpoint, and genomic mutations on CTLA-4 have been associated with immune deficiency, leading to human autoimmune diseases." (PMID 34201650, 2021). "Cytotoxic T-lymphocyte-associated protein 4 (CTLA-4), PD-1, and PD-L1 are co-inhibitors which stop the immune response to prevent autoimmune diseases." (PMID 34357126, 2021). "A number of CTLA4 and PD-l1 polymorphisms have been associated with autoimmune disorders such as rheumatoid arthritis and autoimmune endocrinopathies." (PMID 34201529, 2021). "Polymorphisms in the CTLA-4 gene are responsible for some autoimmune diseases, such as Hashimoto thyroiditis, type 1 diabetes, and Addison’s disease." (PMID 34236546, 2021). "When Ctla4 deficiency is confined to Tregs, mice exhibit delayed lymphoproliferation and fatal T cell-mediated autoimmune disease (including pulmonary lymphocytic infiltrates) by 7 weeks of age." (PMID 35154081, 2021). "Consistent with this, SNPs in CTLA4 are risk variants for various autoimmune disorders; however, it is unclear which CTLA4 variants are causative and by what mechanism they confer susceptibility to autoimmunity." (PMID 33746952, 2021). "In murine models, CTLA-4 deficiency has shown to cause lethal lymphoproliferative disorders, while PD-1 deficiency induces milder autoimmune diseases compatible with survival." (PMID 36046145, 2021). "Regarding shared susceptible genes, the CTLA-4 +49 G allele was found to increase the risk of dengue infection and the viral load, and was also indicated to be associated with autoimmune diseases and SLE." (PMID 34805205, 2021).